MMP9 (matrix metallopeptidase 9)
Diseases named in the same sentence as MMP9 in open-access papers (continued):
Sharing a sentence is not in itself a finding about the gene and the disease.
breast carcinoma (continued). "The cooperative role between lipocalin-2 and MMP-9 in breast cancer progression prompted us to investigate the concomitant presence of MMP-9 and we found the positive correlation between lipocalin-2 and MMP-9 in serum from breast cancer patients." (PMID 22640376, 2012). "In the present study, we examined the association between preoperative serum levels of lipocalin-2 and MMP-9 and disease-free survival (DFS) and determined the potential of both proteins as noninvasive biomarkers in predicting the recurrence of breast cancer." (PMID 22640376, 2012). "For this reason, we first analyzed the mRNA expression levels of MMP-2, MMP-9, MMP-14, TIMP-1, TIMP-2, TIMP-3 and RECK, in the same panel of five human breast cancer cell lines, but now maintained in culture until achieving 80-90% confluence." (PMID 22260435, 2012). "MMP-9 and VEGF were induced via the NF-κB pathway in an emmprin-dependent manner in osteotropic breast cancer cells." (PMID 22640183, 2012). "Among the several MMPs previously related to breast cancer progression, the gelatinases (MMP-2 and MMP-9) stand out for their collagen type IV specific degradation capacity, in view of the fact that it is an abundant ECM component." (PMID 22260435, 2012). "Enhanced MMP9 expression has been observed in astroglioma cell lines following OSM exposure and breast cancer cells treated with OSM demonstrated increased VEGF production associated with detachment and invasion." (PMID 21481226, 2011). "On the other hand, B1R stimulation induces release of MMP-2 and MMP-9 via an ERK-dependent pathway in estrogen-sensitive and-insensitive breast cancer cells." (PMID 21729302, 2011). "Breast cancer cells secrete much higher level of M-CSF, OSM, MIP-2/CXCL-2, MMP-9 and TIMP-1 than ES cells, which are factors correlated with tumor metastasis." (PMID 22174624, 2011). "One model of pterostilbene against metastasis is that pterostilbene exerts an inhibitory effect on p38 kinase pathway where it regulates HRG-β1-driven MMP-9 induction, invasion and migration of MCF-7 breast cancer cells." (PMID 19617202, 2011). "Herein, the role of pterostilbene against HRG-β1/HER2-induced MMP-9 expression and invasion of MCF-7 human breast cancer cells has been first investigated." (PMID 19617202, 2011). "In this study, the mRNA and protein levels of MMP-2, MMP-9, MMP-13, MT1-MMP and TIMP-2 in benign and malignant mammary tumors were thoroughly analyzed." (PMID 21726449, 2011). "Melatonin exerts an inhibitory effect on breast cancer cell invasion through down-regulation of the p38 pathway, and inhibition of MMP-2 and MMP-9 expression and activity." (PMID 21167057, 2010). "Our present findings demonstrate that both the α and the β isoforms of HSP90 are secreted by cultured MDAMB453 human breast cancer cells and interact with matrix metalloproteinases, MMP2 and MMP9." (PMID 20602761, 2010). "Zaman's work on colorectal and breast cancer patients specifically showed increased concentrations in VEGF-A and MMP-9 plasma levels due to malignancy." (PMID 20445741, 2010). "The breast cancer patients saw a decrease in the average VEGF-A plasma concentration from 52.9 μg/mL to 43.8 μg/mL and their MMP-9 levels dropped from an average of 237.8 ng/mL to 109.6 ng/mL." (PMID 20445741, 2010). "Our results demonstrated that melatonin, via its MT1 receptor, plays an inhibitory role in breast cancer cell invasion, possibly by specifically downregulating the p38 MAPK signaling pathway, and the downstream activity of MMP-2 and MMP-9." (PMID 21167057, 2010). "Our results showed that both HSP90α and HSP90β are secreted by MDAMB453 human breast cancer cells and interact with MMP2 and MMP9." (PMID 20602761, 2010). "The expression of two genes, Matrixmetalloproteinase-13 (MMP-13) and Matrixmetalloproteinase-9 (MMP-9), that are known to be involved in invasion and have been shown to be regulated by Runx2 in metastatic breast cancer cells, was examined." (PMID 20591170, 2010).
breast carcinoma (continued). "Our results demonstrated that melatonin suppresses the in vitro invasive potential of breast cancer cells by altering the phosphorylation of p38 MAPK and the downstream activity of MMP-2 and MMP-9." (PMID 21167057, 2010). "Our results also show that cholesterol depletion in breast cancer cells downregulates ERK-and JNK-dependent pathways, thereby leading to downregulation of uPAR and MMP-9 expression." (PMID 21106094, 2010). "This study provides evidence that inactivation of PI3K/Akt signaling pathway by ANT2 shRNA down-regulates MT1-MMP, MMP2, and MMP9 expression and activity as well as VEGF expression in a HER2/neu-overexpressing breast cancer cell line." (PMID 20650008, 2010). "And in another study, breast cancers induced by Wnt-1 overexpressed a series of MMPs, including MMP-2 and MMP-9, except MMP-7, a long held Wnt target gene in intestinal tumors." (PMID 19586554, 2009). "Our findings suggest that both MMP-9 and NGAL serum levels are correlated with breast cancer progression since they seem to follow a gradual increase with disease severity, supporting their potential role as early biomarkers." (PMID 19889214, 2009). "Biochanin A-mediated inhibition of MMP-9 enzyme activity and MT-MMP1 protein expression suggests that biochanin A can block invasion promoting signaling mechanisms in SK-BR-3 breast cancer cells." (PMID 20169097, 2009). "The tissue levels of at least MMP-1, MMP-2, MMP-9, MMP-11, membrane type (MT) 1-MMP, tissue inhibitors of metalloproteinases (TIMP) 1 and TIMP-2 have been correlated with poor outcome of breast cancer patients." (PMID 19243594, 2009). "The classifiers were able to distinguish normal tissue from breast cancer with a classification performance of AUC = 0.82 ± 0.04 with the proteins MIF, MMP-9, and MPO." (PMID 19476629, 2009). "To further address a possible role for MMPs in IL-17-dependent invasiveness of breast cancer cell lines, we assayed the supernatants from IL-17-treated and control MDA-MB231 and MDA-MB453 cells for the presence of MMP-2, MMP-3, MMP-9 and TIMP-1." (PMID 19014637, 2008). "Previous studies have examined the value of biomarkers such as carcinoembryonic antigen, CA 15-3, MMP-2, MMP-9, tissue polypeptide antigen (TPA), tissue polypeptide-specific antigen (TPS), EGFR, and HER-2/neu in predicting response to NAC for breast cancer." (PMID 18474099, 2008). "Taken together, we suggest that TNF-α-induced MMP-9 expression and cell invasion are decreased by BBR through the suppression of AP-1 DNA binding activity in MDA-MB-231 human breast cancer cells." (PMID 19052522, 2008). "Matrix metalloproteinase-1 was immunohistochemically detected in 88.3% of breast carcinomas, MMP-2 in 42%, MMP-7 in 87.4%, MMP-9 in 74%, MMP-11 in 89.3%, MMP-13 in 73.3%, MMP-14 in 90%, TIMP-1 in 95%, TIMP-2 in 87% and TIMP-3 in 82.3%." (PMID 17848954, 2007). "This study revealed that NRG-1 activates MMP-9 via multiple signaling pathways (ERK-, PKC-, and p38 kinase-pathway) in human breast cancer cell lines." (PMID 16901352, 2006). "Under these conditions, four secreted MMPs were identified: MMP-1, MMP-3, MMP-9, and MMP-13 and the membrane-anchored MMP, MT1-MMP in all 3 breast cancer cell lines (MDA-231 cells shown, results similar in all 3 breast cancer cell lines)." (PMID 15701164, 2005). "Recent work on breast cancer patients has suggested that MMP-2 negativity may be linked with a favourable prognosis in node-negative breast carcinoma and that high activity levels of plasma MMP-9 in breast cancer patients are associated with a worst overall survival rate." (PMID 15054465, 2004).
breast carcinoma (continued). "Chemotherapies such as paclitaxel and 5-Fluorouracil (5-FU), commonly used in breast cancer, have been demonstrated to increase brain-barrier permeability to tumor cells, especially through the BCSFB due to upregulation of MMP-9 leading to Claudin-6 downregulation in the choroid plexus cells." (PMID 40076927, 2025). "Our complex network model, which involves potential molecular and cellular factors in the pathogenesis of breast cancer, indicated that the most impactful factors on the network as a whole were MMP2 and MMP9, with statistically significant results (p = 0.01468)." (PMID 40259907, 2025). "Furthermore, SDC3 depletion significantly upregulated MMP1, and downregulated MMP9 in MDA-MB-231 cells, suggesting a multifunctional role of the molecule in modulating migration and invasion in breast cancer." (PMID 41148827, 2025). "MMP-9 enhances extracellular proteolysis and is upregulated by the metalloprotease-disintegrin ADAM8, which is highly expressed in all BMs but particularly breast cancer cells." (PMID 40076927, 2025). "A pilot investigation on breast cancer patients undergoing traditional and hypofractionated radiation therapy suggested that MMPs (specifically MMP-3 and MMP-9) and TIMP4 could be valuable prognostic and predictive biomarkers." (PMID 41002293, 2025). "Studies have revealed that chemotherapy-induced neutrophil extracellular traps (NETs) capture tumor-derived TGF-β via integrin αvβ1 and activate this factor using MMP-9, further promoting the EMT process, thereby reducing the chemotherapy efficacy against breast cancer lung metastasis." (PMID 40568594, 2025). "Furthermore, HA inhibited EMT and osteoblast activators in breast cancer cells, including MMP‐9 and MMP‐13, which regulate breast cancer‐induced osteolysis." (PMID 39947253, 2025). "Additionally, PA exerts anti-cancer effects by interfering with key signaling cascades; for instance, it blocks the NF-κB/ERK/mTOR pathway and inhibits MMP-9 and FAK expression in growth factor-stimulated breast cancer cells." (PMID 40535769, 2025). "Furthermore, E2-ERα signaling drives MMP-2, MMP-9, and MT1-MMP upregulation, promoting ECM remodeling and thereby enhancing breast cancer cell invasion and migration, while ERβ has also been found to regulate the expression of MMP-2 and MMP-7." (PMID 41228316, 2025). "In breast cancer, CD147 is frequently overexpressed and significantly contributes to tumor progression by promoting the production of matrix metalloproteinase 9 (MMP-9), which degrades the extracellular matrix, and vascular endothelial growth factor (VEGF), which supports angiogenesis." (PMID 40265417, 2025). "However, in a different study, PEDF inhibited breast cancer cell migration and invasion by downregulating MMP2 and MMP9 via p-ERK and p-AKT signalling pathways, and fibronectin, but in contrast, failed to impose itself on EMT." (PMID 40649783, 2025). "In particular, the downregulation of MMP-9 following dual receptor inhibition aligns with the migration and dissemination results observed in the MCF-7 cells, indicating the less metastatic nature of this breast cancer cell line." (PMID 40867236, 2025). "AR extract at 500 mg/kg body weight demonstrated the highest anti-neoplastic efficacy in a DMBA-induced rat mammary tumour model, significantly reducing tumour progression, oxidative stress, pro-inflammatory cytokines (TNF-α and NF-κB), and expression of Ki-67, MMP-9, and VEGF markers." (PMID 41158126, 2025). "Although it is known that TGF-β or TNF-α stimulation regulates the MMP-9 expression in various cells, it remains unclear how the combined TGF-β/TNF-α stimulation modulates MMP-9 expression in breast cancer cells." (PMID 39351229, 2024). "We recognize that a subset of the genes we identified in our analysis of this dataset are opposite of what has been reported in prior work, specifically MMP9 and ESR1, as being upregulated in Letrozole-resistant breast cancer tumors, which agrees with our findings." (PMID 39057065, 2024).
breast carcinoma (continued). "Neutrophils exposed to breast cancer cell-derived supernatant displayed heightened levels of interleukin-1β (IL-1β), CC-chemokine ligand-2-4 (CCL2, CCL3, and CCL4), inducible nitric oxide synthase (iNOS), and matrix metallopeptidase-9 (MMP9)." (PMID 38474175, 2024). "For this reason, we decided to evaluate whether Brazilin influence the expression of EMT markers such as E-cadherin, vimentin, and Twist, the secretion levels of MMP-2 and MMP-9 and the invasion of MCF7 and MDA-MB-231 breast cancer cells." (PMID 38737746, 2024). "Also, Balakrishnan and co-workers reported the inhibition of MMP-2 and MMP-9 protein expression in MCF-7 and MDA-MB-231 breast carcinoma cells after quercetin treatment." (PMID 39335164, 2024). "Given that MMP2 and MMP9 play important roles in degrading type IV collagen with MMP9 being particularly influential in breast cancer metastasis, we sought to determine if GATA4 might also counteract breast cancer metastasis by modulating MMP9." (PMID 38653973, 2024). "Additionally, the concentrations of MMP-9 and ICAM-1 were measured in the MDA-MB-231 breast cancer cells after 24 h of incubation with Les-6287, as well as doxorubicin." (PMID 39199694, 2024). "Moreover, gelatin gel zymography analysis of isolated MMP-2 utilizing breast cancer cells (MDA-Mb-231) indicates a strong and direct interaction between Myr and MMP-2 and blocks breast cancer metastasis by lowering the action of MMP-2 and MMP-9." (PMID 38672151, 2024). "MMP9 has been shown to contribute to TGF-β-induced invasion in MII cells, which may be relevant to the mechanism of action of C1orf106 in our breast cancer model." (PMID 39329715, 2024). "For example, by downregulating phospho-ERK in pancreatic cancer cells, resveratrol inhibits the MAPK signaling pathway and nicotine’s potential to stimulate cell growth; meanwhile, kaempferol is able to inhibit the activity of MMP-9, by deactivating the MAPK/AP-1 pathway in breast cancer cells." (PMID 38540096, 2024). "In breast cancer, it has been described that KP10 can stimulate the migration and invasion of ERα-negative breast cancer cells via transactivation of the EGFR pathway and increased MMP-9 activity." (PMID 39199311, 2024). "Taken together, co-expression of elevated MMP-9 with of TGF-β and TNF-α in the human breast cancer tissues is corroborated to our in vitro findings indicating the synergistic role of TGF-β and TNF-α in potentiating MMP-9 in breast cancer cells." (PMID 39351229, 2024). "The aim of this study was to evaluate the antioxidant activity of four different dietary polyphenolic compounds and their ability to inhibit ROS production in THP-1 macrophages and the activity of MMP-2 and MMP-9 in both THP-1 macrophages and in sera from patients with breast cancer." (PMID 38675538, 2024). "Tang and co-workers reported that, in breast cancer cells, quercetin significantly inhibited the protein expression of MMP-2 and MMP-9 and increased the TIMP-1 and TIMP-2 levels in a concentration-dependent manner; it also suppressed the activity of MMP-2 and MMP-9 based on gelatin zymography." (PMID 39335164, 2024). "The authors also suggested that MMP-9 and TIMP-3 could be proposed as predictors of radiotherapy toxicity in breast cancer, accepting that they could be useful prognostic biomarkers for this pathology." (PMID 38203696, 2023). "Interestingly, breast cancer MDA-MB-231 and T47D cells that had NAT1 gen deleted showed increased MMP-9 expression." (PMID 38069210, 2023). "Hence, BTK inhibition shall inhibit the expression of MMP-9 initiated by TPA, thereby suppressing breast cancer metastasis." (PMID 36986499, 2023). "Studies on breast cancer showed that UTI may inhibit MCF-7 cell line proliferation and the growth of xenograft breast cancer in nude mice by reducing the expression of the receptor 4 for the CXC chemokine and MMP-9." (PMID 36414878, 2023).
breast carcinoma (continued). "Although MMP-9 transcription in MCF-7 breast cancer cells was not sensitive to E2 or ethanol, MMP-2 transcription was stimulated by these compounds." (PMID 36310188, 2023). "The results showed that adipocytokines from in vitro adipocytes mimicking obesity increased the stabilization of β-catenin and the expression of MMP-9 protein in MCF-7 and MDA-MB-231 breast cancer cells, in comparison to pre and mature adipocytes, or in untreated conditions." (PMID 38068928, 2023). "Moreover, using transwell membrane cultures, it has been shown that ADAM8 promotes the transendothelial migration in the initial steps of the metastastatic cascade through elevation of MMP9 and shedding of PSCL-1 of the cell surface of breast cancer cells." (PMID 37287457, 2023). "In particular, prolonged exposure of breast cancer cell lines to TNFα induces EMT through the activation of IKKβ and NF-κB, cancer cell migration via the MAPK/ERK signaling pathway, and MMP2 and MMP9 expression." (PMID 36835413, 2023). "However, breast cancer cells display activation of NF-κB and upregulation of expression of IL-6, TGF-β, VEGF, and matrix-metalloproteinase 9 (MMP9)." (PMID 37822929, 2023). "Interestingly, the knockdown of PLAU along with MMP9, which is also FRA-1-regulated in breast cancer, restores the cell–cell adhesion and inhibits the expression of EMT-associated genes in BCCs." (PMID 37176013, 2023). "The inhibitory effect of curcumin on TGF-β-induced expression of MMP9 has also been previously reported in MDA-MB-231 breast cancer cells, so it is plausible that the inclusion of curcumin into the treatment media would enhance the suppressive effect of MPP on MMP9 gene expression." (PMID 36687217, 2023). "CXCL1 induces breast cancer cell migration through the activation of extracellular signal-regulated kinase (ERK) MAPK, which increases the expression of matrix metalloproteinase 2 (MMP2) and matrix metalloproteinase 9 (MMP9)." (PMID 37108425, 2023). "MMP9 and ADAM8 (a disintegrin and metalloprotease) co-regulation has been demonstrated to promote breast cancer BM, with ADAM8 reported to upregulate MMP9 and the shedding of P-selectin glycoprotein ligand (PSGL-1) from breast cancer cells." (PMID 37190188, 2023). "Numerous studies have examined an association between MMP-2, MMP-9, and MMP-11 expression and clinicopathological characteristics of breast cancer (BC); however, no research has been done on the MMP expression levels in BC cases from Ethiopia." (PMID 37798646, 2023). "For instance, in a spontaneous mouse model of breast cancer (MMTV-PyMT mice), IVM helped to demonstrate that doxorubicin treatment induces recruitment of myeloid cells expressing matrix metalloproteinase 9 (MMP9) into the tumor via the CCL2/CCR2 chemokine/chemokine receptor axis." (PMID 37908739, 2023). "In a previous study, the presence of C18:1 promoted MMP-9 secretion through a PKC, Src, and EGFR-dependent pathway suggesting that C18:1 may have a crucial role in the invasion process and metastasis in breast cancer." (PMID 37371132, 2023). "Hence, it is meaningful to synthesize a dual-targeted imaging probe that combines MMP-9- and fibronectin-targeting abilities for accurate diagnosis and FMI-guided surgery for breast cancer." (PMID 36978072, 2023). "Matrix metalloproteinase-9 (MMP-9) portrays a distinct function in the initiation, progression, invasion and tumor microenvironment modulation in several cancers, including colon cancers, lung cancers, brain cancers, melanomas and breast cancer." (PMID 37372062, 2023). "Quercetin could inhibit the proliferation and invasion of breast cancer cells by downregulating the expression of MMP2 and MMP9." (PMID 35379271, 2022). "MMP-2 and MMP-9 were also upregulated in breast cancer tissue but were not in adjacent normal tissue." (PMID 35742125, 2022).